CRHR1 (corticotropin releasing hormone receptor 1)
Diseases named in the same sentence as CRHR1 in open-access papers (continued):
Sharing a sentence is not in itself a finding about the gene and the disease.
tumor (13 papers, 2007 to 2024). "We found that the Crhr1 deficiency confers the tumor-suppressing effect in the Apcmin/+ mouse model, while the Crhr2 deficiency exacerbates the tumorigenicity in these two experimental models." (PMID 33494263, 2021). "Crhr1 deficiency not only inhibits the expression of tumor-promoting cyclooxygenase 2, but also upregulates tumor-suppressing phospholipase A2 in Apcmin/+ mice; however, Crhr2 deficiency does not change these expressions." (PMID 33494263, 2021). "Taken together, these data demonstrate that the Crhr1 deficiency not only suppresses tumor development and growth in the Apcmin/+ mouse, but also ameliorates the disease severity." (PMID 33494263, 2021). "In conclusion, Crhr1 deficiency confers tumor-suppressing effects in Apcmin/+ mice, but Crhr2 deficiency worsens the tumorigenicity in both Apcmin/+ and AOM/DSS-treated mice." (PMID 33494263, 2021). "In conjunction with reduced Cox2 levels, our data suggested that upregulated Pla2 expression plays a crucial role in eliciting the tumor-protective effect by Crhr1 deficiency." (PMID 33494263, 2021). "In contrast, our data demonstrate that Crhr1 deficiency markedly suppresses tumor development and growth in Apcmin/+ mice." (PMID 33494263, 2021). "Intriguingly, a study has previously showed that Crhr1−/− mice develop much fewer tumors when the mice are tested in the AOM/DSS model, suggesting that Crhr1 deficiency can induce tumor-suppressive effects in this model." (PMID 33494263, 2021). "By contrast, regarding CRH/CRHR1 signaling, a pro-inflammatory and, therefore, tumor-promoting effect, was observed in colitis-associated cancer." (PMID 32429087, 2020). "Another pathway active during the Vascular Endothelial Growth Factor (VEGF)-induced tumor angiogenesis is the CRH/CRHR1 signaling, as one of the mechanisms in colitis-associated CRC." (PMID 32429087, 2020). "Accordingly, we hypothesize that Crhr1 deficiency not only reduces the expression of Cox2, but also increases the Pla2 level, thereby, suppressing tumor development and growth." (PMID 33494263, 2021). "Therefore, it is reasonable to believe that reduced Cox2 expression by Crhr1 deficiency may be associated with the tumor-protective effect observed in both Apcmin/+; Crhr1−/− mice and Apcmin/+; Crhr1+/− mice." (PMID 33494263, 2021). "In addition, Crhr1 deficiency upregulates the level of Pla2 in the tumor tissues." (PMID 33494263, 2021). "Crhr1 deletion suppresses the tumor development and growth in Apcmin/+ mice, while Crhr2 deficiency exacerbates the tumorigenicity." (PMID 33494263, 2021). "Taken together, our findings suggest that blocking CRHR1-mediated responses inhibit tumor development and growth in an Apcmin/+ background, while inhibiting CRHR2-mediated responses promote tumorigenesis." (PMID 33494263, 2021). "Our study sets the initiative for the consideration of CRHR1 antagonists in an effort to reduce tumour immune defenses." (PMID 17667919, 2007). "In contrast to the tumor suppressing effect observed in the Apcmin/+ mice, Crhr1 deficiency does not alter tumorigenesis in the AOM/DSS model." (PMID 33494263, 2021). "Moreover it has been demonstrated that the CRH ligand Ucn promotes hepatic cancer cell migration by up-regulating cPLA2 expression via CRHR1 whereas it suppressed tumor cell migration by down-regulating iPLA2 expression via CRHR2." (PMID 27695045, 2016). "Although no alteration was observed in the expression of CRHRs among the three stage-groups of tumours, more stage IV than stage II tumours simultaneously expressed the CRH, CRHR1 and FasL peptides." (PMID 17667919, 2007). "Depending on the diversity of the microflora, therefore, the tumor-suppressing effect of Crhr1 deficiency could be recapitulated with different outcomes, providing an explanation why we could not observe the tumor-suppressing effect of Crhr1 deficiency in the AOM/DSS model." (PMID 33494263, 2021).
tumor (continued). "Furthermore, tumour advancement was positively correlated with the percentage of tumours simultaneously expressing CRH, CRHR1 and FasL." (PMID 17667919, 2007). "The percentage of tumours simultaneously expressing CRH, CRHR1 and FasL was higher in stage IV compared to stage II tumours, although this difference was not statistically significant." (PMID 17667919, 2007).
infection (10 papers, 2009 to 2026). The state of being infected such as from the introduction of a foreign agent such as serum, vaccine, antigenic substance or organism. "Although these findings suggest that CRHR1 variants may contribute to cognitive vulnerability following infection, the limited sample size of our study precludes drawing conclusions about their prevalence in the broader Armenian population or their definitive pathogenic role." (PMID 41614899, 2026). "Inclusion of a SARS-CoV-2-negative control group would be necessary to determine infection-specific effects on CRHR1 gene variation." (PMID 41614899, 2026). "Ex vivo recordings were carried out in slices from mice, >5 weeks after infection with a control GFP or the shRNAmir virus to ensure sufficient degradation of CRHR1." (PMID 40830097, 2025). "Limitations of the study are implicit in the limited range and quantity of infection by the virus: only a minority of endogenous CRHR1 expressing neurons co-expressed the viral reporters." (PMID 39692887, 2024). "The corticotropin-releasing hormone receptor 1 (CRHR1), a key regulator of stress and neuroendocrine responses, represents a biologically plausible candidate for post-infection cognitive vulnerability." (PMID 41614899, 2026).
cancer (6 papers, 2013 to 2024). A tumor composed of atypical neoplastic, often pleomorphic cells that invade other tissues. "There are no studies in literature comparing CRHR1 expression in carcinomas and premalignant lesions so far." (PMID 37382757, 2024).
neurological disorders (5 papers, 2013 to 2024). "The 439-kb microduplication at the 17q21.31 locus, associated with neurological diseases encompasses MAPT, IMP5, CRHR1, and STH." (PMID 38812061, 2024). "Lastly, two genes in the inversion, CRHR1 and MAPT, are not located in copy number variation regions 1–4, but their duplication is correlated with neurological diseases." (PMID 38812061, 2024).
neurodegenerative disease (4 papers, 2018 to 2023). A disorder of the central nervous system characterized by gradual and progressive loss of neural tissue and neurologic function. "We present this hypothesis cautiously due to CRHR1’s location in a linkage disequilibrium block containing genes like MAPT, which may be involved in neurodegenerative diseases and cortical anatomy." (PMID 35947372, 2022).
inflammation (1 paper, 2015). Aberrant reaction of the microcirculation characterized by movement of fluid and leukocytes from the blood into extravascular tissues. "A previous study on intestinal inflammation showed that CRH via CRHR1 increased phosphorylation of Akt in human intestinal microvascular endothelial cells." (PMID 26110874, 2015).
intestinal disorder (1 paper, 2017). A non-neoplastic or neoplastic disorder that affects the small or large intestine. "It is notable that some of the CRHR1-associated beneficial effects could be specific to NEC, since the mechanism of NEC development does not resemble that of intestinal disorders that develop in adulthood." (PMID 28492284, 2017).
skin disorder (1 paper, 2026). Any deviation from the normal structure or function of the skin or subcutaneous tissue that is manifested by a characteristic set of symptoms and signs. "To better understand the link between stress and skin disorders, we aimed to investigate the differential expression of CRHR1 and CRHR2 in keratinocytes, depending on their level of differentiation." (PMID 41751472, 2026).
CRHR1 also shares sentences with these, for which no sentence is quoted: alcoholism (11 papers); Alzheimer disease (8); Anorexia (5); Insulin resistance (5); Adrenal insufficiency (4); congenital adrenal hyperplasia (4); epilepsy (4); type 2 diabetes (3); alcohol addiction (2); allergic disease (2); aspergillosis (2); autoimmune disease (2); bipolar disorder (2); bladder disorder (2); cognitive decline (2); corticotrope adenomas (2); immune diseases (2); nicotine dependence (2); pituitary tumor (2); respiratory diseases (2); Rett syndrome (2); subarachnoid haemorrhage (2); ulcerative colitis (2); urticaria (2); vitiligo (2); adrenal tumors (1); allergic asthma (1); allergic bronchopulmonary aspergillosis (1); allergies (1); alopecia (1).
A further 70 diseases each share a sentence with CRHR1 in 1 paper.